H3-4 (H3.4 histone, cluster member)
Description:
Core component of nucleosome. Nucleosomes wrap and compact DNA into chromatin, limiting DNA accessibility to the cellular machineries which require DNA as a template. Histones thereby play a central role in transcription regulation, DNA repair, DNA replication and chromosomal stability. DNA accessibility is regulated via a complex set of post-translational modifications of histones, also called histone code, and nucleosome remodeling.
Synonyms: H3t; H3FT; HIST3H3; H3/g; H3.4; H3C16
Tractability: Small molecule: a structure with a bound ligand is known. PROTAC: UniProt records ubiquitination sites on it; ubiquitination databases record sites on it.
Gene: Protein-coding gene on chromosome 1 (228,424,845 to 228,425,360, reverse strand). Ensembl gene ENSG00000168148.
Subcellular location: Nucleus; Chromosome
Subcellular location (Human Protein Atlas): Nucleoplasm
Pathways (Reactome):
DNA Repair: Cleavage of the damaged purine; Cleavage of the damaged pyrimidine; Nonhomologous End-Joining (NHEJ); Processing of DNA double-strand break ends; Recognition and association of DNA glycosylase with site containing an affected purine; Recognition and association of DNA glycosylase with site containing an affected pyrimidine; Recruitment and ATM-mediated phosphorylation of repair and signaling proteins at DNA double strand breaks
Cell Cycle: Condensation of Prophase Chromosomes; G2/M DNA damage checkpoint; Inhibition of DNA recombination at telomere; Packaging Of Telomere Ends
Reproduction: Meiotic recombination; Meiotic synapsis
Cellular responses to stimuli: DNA Damage/Telomere Stress Induced Senescence
Signal Transduction: Formation of the beta-catenin:TCF transactivating complex
Gene Ontology:
Molecular function: protein binding; structural constituent of chromatin; nucleosomal DNA binding; DNA binding; protein heterodimerization activity
Biological process: nucleosome assembly; chromatin organization; heterochromatin formation; spermatogonial cell division
Cellular component: chromosome, telomeric region; extracellular exosome; nucleoplasm; nucleosome; nucleus; chromosome; condensed nuclear chromosome; heterochromatin
Genetic constraint (gnomAD): Loss-of-function variants: 10 observed, 7.33 expected, observed/expected ratio (o/e) 1.36, 90% interval 0.82 to 1.9. That is too few expected variants to judge how well the gene tolerates losing a copy. Missense variants: 298 observed, 216.13 expected, observed/expected ratio (o/e) 1.38, 90% interval 1.25 to 1.52. Synonymous variants: 138 observed, 91.47 expected, observed/expected ratio (o/e) 1.51, 90% interval 1.31 to 1.74.
Homologues: Orthologues: chimpanzee H3-4 (99% identical), macaque H3-4 (99% identical), mouse H3f4 (98% identical), Drosophila melanogaster His3:CG33812 (96% identical), zebrafish si:ch1073-153i20.2 (96% identical), zebrafish si:ch211-113a14.20 (96% identical), zebrafish si:ch211-113a14.23 (96% identical), zebrafish si:ch211-113a14.27 (96% identical), zebrafish zgc:173552 (96% identical), Caenorhabditis elegans his-17 (94% identical), Caenorhabditis elegans his-2 (94% identical), Caenorhabditis elegans his-32 (94% identical), and 9 more. Paralogues in human: H3C1 (97% identical), H3C10 (97% identical), H3C11 (97% identical), H3C12 (97% identical), H3C2 (97% identical), H3C3 (97% identical), H3C4 (97% identical), H3C6 (97% identical), H3C7 (97% identical), H3C8 (97% identical), H3C13 (96% identical), H3C14 (96% identical), and 8 more.
Diseases named in the same sentence as H3-4 in open-access papers:
H3-4 is named in the same sentence as 4 diseases in open-access papers, as found by Europe PMC text mining. Sharing a sentence is not in itself a finding about the gene and the disease.
H3-4 shares sentences with these, for which no sentence is quoted: cancer (3 papers); tumor (2); infertile (1); liver cancer (1).